CSTB (cystatin B)
Description:
This is an intracellular thiol proteinase inhibitor. Tightly binding reversible inhibitor of cathepsins L, H and B.
Synonyms: CST6; STFB; PME; CPI-B; EPM1; EPM1A; ULD
Tractability: Antibody: its Gene Ontology location is reachable by antibodies, with high confidence. PROTAC: ubiquitination databases record sites on it; its protein half-life has been measured.
Gene: Protein-coding gene on chromosome 21 (43,772,511 to 43,776,579, reverse strand). Ensembl gene ENSG00000160213.
Subcellular location: Cytoplasm; Nucleus
Subcellular location (Human Protein Atlas): Cytosol; Nucleoli
Pathways (Reactome):
Immune System: Neutrophil degranulation
Gene Ontology:
Molecular function: cysteine-type endopeptidase inhibitor activity; endopeptidase inhibitor activity; protease binding; RNA binding
Biological process: negative regulation of proteolysis
Cellular component: cytoplasm; cytosol; extracellular exosome; extracellular matrix; extracellular region; nucleolus; nucleus; ficolin-1-rich granule lumen; secretory granule lumen; tertiary granule lumen
Genetic constraint (gnomAD): Loss-of-function variants: 7 observed, 7.47 expected, observed/expected ratio (o/e) 0.94, 90% interval 0.53 to 1.68. That is too few expected variants to judge how well the gene tolerates losing a copy. Missense variants: 124 observed, 116.64 expected, observed/expected ratio (o/e) 1.06, 90% interval 0.92 to 1.23. Synonymous variants: 56 observed, 51.73 expected, observed/expected ratio (o/e) 1.08, 90% interval 0.87 to 1.35.
Gene-disease validity (ClinGen):
ClinGen rates the evidence that CSTB causes each of these diseases.
Unverricht-Lundborg syndrome (autosomal recessive): Definitive. Unverricht-Lundborg disease (ULD) is a rare progressive myoclonic epilepsy disorder characterized by action- and stimulus-sensitive myoclonus, and tonic-clonic seizures with ataxia, but with only a mild cognitive decline over time.
genetic developmental and epileptic encephalopathy (autosomal recessive): Moderate. A complex neurodevelopmental disorder characterized by a range of developmental delays and epileptic encephalopathy phenotypes.
Homologues: Orthologues: chimpanzee CSTB (99% identical), pig CSTB (85% identical), macaque CSTB (83% identical), dog CSTB (82% identical), mouse Cstb (79% identical), rat Cstb (79% identical), guinea pig CSTB (73% identical), rabbit CSTB (64% identical), zebrafish cst14a.2 (55% identical), zebrafish cst14a.1 (54% identical), tropical clawed frog cstb (44% identical). Paralogues in human: CSTA (53% identical).
Diseases named in the same sentence as CSTB in open-access papers:
CSTB is named in the same sentence as 148 diseases in open-access papers, as found by Europe PMC text mining. Sharing a sentence is not in itself a finding about the gene and the disease. The quoted sentences say what the papers report.
progressive myoclonus epilepsy (22 papers, 2011 to 2024). A rare group of disorders characterized by the development of myoclonic and tonic-clonic epileptic seizures associated with progressive degeneration of the nervous system. "One of the main symptoms of the disorder is myoclonus epilepsy, and we know that 5-HT and the KP pathways change in patients with Unverricht–Lundborg disease, which is a type of progressive myoclonus epilepsy, and in cystatin B (CSTB)-deficient mice." (PMID 38338981, 2024). "EPM1, an autosomal recessive disorder, is the most common form of progressive myoclonus epilepsy and associated with mutations in the cystatin B (CSTB) gene and its promoter." (PMID 37719765, 2023). "Copy number expansions in the VNTR upstream of CSTB have been previously associated with progressive myoclonic epilepsy (EPM1)." (PMID 33849068, 2021). "The decreased CSTB expression associated with the expansion of VNTR was also described in patients with progressive myoclonus epilepsy." (PMID 33276684, 2020). "Mutations of CSTB leads to progressive myoclonus epilepsy (EPM1), which is an inherited and lethal autosomal disease." (PMID 31139015, 2019). "Unverricht-Lundborg disease (ULD) is a common form of progressive myoclonic epilepsy caused by mutations in the cystatin B gene (CSTB) that encodes an inhibitor of several lysosomal cathepsins." (PMID 30208654, 2018). "Mutations in CSTB are associated with progressive myoclonus epilepsies (PMEs) in Unverricht-Lundborg disease (EPM1; OMIM254800) a disease that shares features with late myoclonic epilepsy observed in DS." (PMID 22140471, 2011). "The loss of the cystatin gene, CSTB, is a model for progressive myoclonus epilepsy which is an inherited neurodegenerative disease and its congruence with AD also may reflect common patterns found in neurodegenerative disorders." (PMID 38236817, 2024). "However, in a model of progressive myoclonus epilepsy of Unverricht–Lundborg type, characterized by the loss-of-function mutation of cysteine protease inhibitor cystatin B (CSTB), microglia were found to be in an activated state as measured by increased expression of interferon-regulated genes." (PMID 33540859, 2021). "Mutations in the cystatin B gene (CSTB), which encodes an inhibitor of several lysosomal cathepsins, result in Unverricht-Lundborg disease (ULD), a form of progressive myoclonic epilepsy with limited pharmacological treatments." (PMID 35250833, 2022). "Mutations of CSTB cause progressive myoclonic epilepsy-1A (EPM1A), the most common form of progressive myoclonic epilepsy." (PMID 31467503, 2019). "Among Hsa21 candidate genes in epilepsy, CSTB, coding for the cystein protease inhibitor cystatin B, is involved in progressive myoclonus epilepsy and ataxia in both mice and human." (PMID 22140471, 2011). "Stefin B (cystatin B) is an inhibitor of endo-lysosomal cysteine cathepsin, and the loss-of-function mutations in the stefin B gene were reported in patients with Unverricht–Lundborg disease (EPM1), a form of progressive myoclonus epilepsy." (PMID 33673502, 2021). "Thus, the associations of the expanded dodecamer repeat from the cystatin B (CSTB) gene promoter with progressive myoclonus epilepsy (EPM1) were identified." (PMID 33276684, 2020). "CSTB may play a critical role in brain physiology because its mutations cause progressive myoclonic epilepsy-1A (EPM1A), the most common form of progressive myoclonic epilepsy." (PMID 31467503, 2019). "It has been reported that dysregulation of cystatin B-cathepsin B signaling may serve as a critical mechanism coupling oxidative stress to neuronal degeneration in progressive myoclonus epilepsy." (PMID 25470616, 2014).
Unverricht-Lundborg disease (20 papers, 2011 to 2025). "Individuals who lack two functional copies of CSTB, develop a genetic form of epilepsy called Unverricht-Lundborg disease, that is progressive and associated with neurodegeneration." (PMID 39841661, 2025). "Progressive myoclonus epilepsy type 1 (EPM1) is an autosomal recessively inherited childhood–adolescence onset neurodegenerative disease caused by mutations in the cystatin B (CSTB gene)." (PMID 38179183, 2023). "Mutations in the gene for human stefin B (cystatin B) cause progressive myoclonic epilepsy type 1 (EPM1), a neurodegenerative disorder." (PMID 36340691, 2022). "Loss-of-function mutations in the stefin B gene (CSTB) gene were reported in patients with Unverricht-Lundborg disease (EPM1)." (PMID 23049497, 2012). "Patients with cystatin B mutations suffer from the Unverricht Lundborg syndrome, a disorder associated with epileptic seizures." (PMID 21794126, 2011). "Biallelic partial loss-of-function mutations in the CSTB gene underlie Unverricht-Lundborg disease (progressive myoclonus epilepsy type 1, EPM1; OMIM 254800), a neurodegenerative disorder that usually manifests during late childhood or early adolescence (Lehesjoki and Kälviäinen, 2020)." (PMID 36533126, 2022). "Mutations in CSTB underlying Unverricht-Lundborg disease (EPM1)." (PMID 22936898, 2012). "Unverricht-Lundborg disease (ULD) is an autosomal recessive neurodegenerative disorder caused by biallelic alterations of the CSTB gene." (PMID 40442775, 2025). "Unverricht-Lundborg disease (ULD) is a rare autosomal recessive neurodegenerative disorder, often caused by biallelic promoter expansions of CSTB gene or, more rarely by point/indel variants." (PMID 40442775, 2025). "Unverricht-Lundborg disease is caused by mutations in the CSTB gene, localized on chromosome 21q22.3, which encodes cystatin B (CSTB): a protease inhibitor that is able to inhibit several lysosomal cysteine proteases in vitro by reversible tight-binding." (PMID 30208654, 2018). "Mutations in the cystatin B gene, coding the protein human stefin B, are the cause for progressive myoclonus epilepsy of type 1 (EPM1), known as Unverricht-Lundborg disease." (PMID 24013380, 2013). "Thus, our findings are not in line with a recent report of high frequency of homozygous or compound heterozygote SCARB2 mutations in patients with isolated PME (clinically resembling Unverricht-Lundborg disease but being negative for CSTB mutations)." (PMID 22032306, 2011). "Thus, in our preclinical systems we aimed to reduce but not completely eliminate CSTB protein, to avoid inducing features of Unverricht-Lundborg disease." (PMID 39841661, 2025).
Ataxia (18 papers, 2009 to 2025). Ataxia refers to impaired coordination of voluntary muscle movement. "A mouse model of ULD that lacks the CSTB gene (Cstb-/-) shows myoclonic seizures, ataxia and progressive neuronal loss together with cerebellar and cortical atrophy that aggravates with age." (PMID 32938505, 2020). "There is a mouse model of ULD that lacks the CSTB gene (Cstb−/−), which reproduces the pathophysiology of the disease: they show myoclonic seizures, ataxia, and progressive neuronal loss." (PMID 32326494, 2020). "Progressive myoclonus epilepsy of Unverricht-Lundborg type (EPM1) is an autosomal recessively inherited neurodegenerative disease, manifesting with myoclonus, seizures and ataxia, caused by mutations in the cystatin B (CSTB) gene." (PMID 24586687, 2014). "The involvement of mitochondrial dysfunction in cystatin B (CSTB) deficiency has been suggested, but its role in the onset of neurodegeneration, myoclonus, and ataxia in the CSTB-deficient mouse model (Cstb−/−) is yet unknown." (PMID 37251643, 2023). "CSTB deficiency leads to alterations in GABAergic signaling, and causes early neuroinflammation followed by progressive neurodegeneration in brains of a mouse model, manifesting as progressive myoclonus and ataxia." (PMID 33281550, 2020). "A CSTB-deficient mouse model (Cstb−/−) mimics key features of EPM1, including myoclonic seizures, ataxia, and progressive gray and white matter loss." (PMID 27894304, 2016). "We also found three other genes that are differentially expressed due to Fxn knockdown, namely, CSTB, NHLRC1 and PMM2 all of which are associated with other disorders manifesting ataxia." (PMID 29257745, 2017). "We selected CSTB as a candidate Hsa21 gene for the increased susceptibility of DS persons to epileptic seizure because of its implication in EPM1, a type of myoclonic epilepsy characterized by stimulus-sensitive myoclonic seizures and slowly progressive cerebellar ataxia." (PMID 22140471, 2011).
epilepsy (17 papers, 2009 to 2025). A brain disorder characterized by episodes of abnormally increased neuronal discharge resulting in transient episodes of sensory or motor neurological dysfunction, or psychic dysfunction. "This concept is prominently supported by the fact that deficiency of the cytosolic inhibitor of cysteine cathepsins cystatin B (also known as Stefin B) causes death of neurons and thereby a rare childhood form of epilepsy called Unverricht‐Lundborg syndrome." (PMID 35203107, 2022). "An interesting candidate for susceptibility to epilepsy in DS is CSTB, a gene located on Hsa21 and shown to be overexpressed in the brain of DS individuals, but whose mouse ortholog is absent in the Ts65Dn model used to test PTZ treatment." (PMID 22140471, 2011). "Mutations in the cystatin B (CSTB) gene cause EPM1 epilepsy in patients." (PMID 32378798, 2020). "Discovery of neuronal apoptosis in the EPM1 mouse model deficient for cystatin B and identification of increased expression of Cstb mRNA and protein in a rat kindling model of epilepsies suggest a physiological role for this protein in the maintenance of normal neuronal structure." (PMID 22140471, 2011). "Evaluating the epilepsy and CMAR panels revealed 5 P/LP variants in genes that generally associate with homozygous recessive inheritance (QARS, CLN8, PPT1, CSTB, and FKRP) in heterozygous decedents, indicating that these are likely incidental findings." (PMID 38229148, 2024). "AR forms of epilepsy can be severe with early-onset, such as epilepsy caused by variants in ALDH7A1, or have onset in adolescence or later as with variants in CSTB." (PMID 35911904, 2022). "Taken together, these results shed new light on the role of CSTB during neurogenesis suggesting that CSTB is involved in correct recruitment and migration of interneurons, an essential developmental process often dysregulated in patients with epilepsy." (PMID 32378798, 2020). "This includes a role of CSTB as a long‐distance signaling molecule crucial for the recruitment of inhibitory neurons, uncovering a possible mechanism through which altered levels of CSTB results in epilepsy." (PMID 32378798, 2020). "Additionally, the Cystatin B gene (CSTB) (−) mouse model, a genetic model used to study epilepsy, falls into this category, suggesting a possible shift in research focus." (PMID 39445198, 2024).
Myoclonus (14 papers, 2009 to 2025). Very brief, involuntary random muscular contractions occurring at rest, in response to sensory stimuli, or accompanying voluntary movements. "To investigate whether CSTB-deficient mouse brains show signs of cellular senescence before the first signs of neuron loss and onset of myoclonus at P30, we focused our further analyses on the time window from the P14 to P30." (PMID 36533126, 2022).
progressive myoclonus epilepsy type 1 (11 papers, 2005 to 2026). "Progressive myoclonus epilepsy type 1 (EPM1) is a rare neurodegenerative disease caused by partial loss of function of cystatin B (CSTB), a cysteine protease inhibitor with known neuroprotective roles." (PMID 41782446, 2026). "Background and Aims: Progressive myoclonic epilepsy type 1 (EPM1) is a neurodegenerative disease caused by biallelic alterations in the cystatin B (CSTB) gene." (PMID 40542572, 2025). "Mutations in the stefin B (cystatin B) gene are the underlying cause of the progressive myoclonus epilepsy of type 1 (EPM1), with features of neurodegeneration." (PMID 25047918, 2014). "Human stefin B (cystatin B) mutations cause progressive myoclonus epilepsy of type 1 (EPM1)." (PMID 30669344, 2019). "CSTB mutations are responsible for progressive myoclonus epilepsy type 1 (EPM1)." (PMID 24452274, 2014).
bladder cancer (8 papers, 2014 to 2025). "Elevated CYTB levels in tissues and urine of bladder cancer patients are associated with tumor grade, stage, and recurrence, suggesting CSTB’s role in influencing malignant behavior through regulation of proteolysis and cellular pathways." (PMID 41463032, 2025). "Logistic multivariate regression analysis showed that preoperative NMP22 and CSTB overexpression was an independent risk factor for postoperative recurrence of bladder cancer (OR = 1.042, 2.307, P < 0.05)." (PMID 35647202, 2022). "Elevated levels of CSTB in tumor samples were related to a higher risk of recurrence and advanced tumor stages in bladder cancer and were linked to a higher risk of tumor metastasis in HCC." (PMID 34504787, 2021). "Some studies have indicated that increased CSTB is related to a poorer prognosis in bladder cancer and a higher risk of tumor metastasis in HCC." (PMID 34504787, 2021). "In this study, our results from benign bladder tissues and cancer cell lines showed that CST3, CST6, CSTA, and CSTB were the predominant isoforms out of the 14 family members expressed by bladder cancer cells." (PMID 40747123, 2025). "Receiver operating curve (ROC) was used to analyze the evaluation value of preoperative NMP22 and CSTB expression in patients with bladder cancer postoperative recurrence." (PMID 35647202, 2022). "NMP22 combined with CSTB detection will help to detect postoperative recurrence of bladder cancer and formulate effective treatment measures in time." (PMID 35647202, 2022). "Logistic multivariate regression method was used to analyze the correlation between preoperative NMP22 and CSTB expression and postoperative bladder cancer recurrence." (PMID 35647202, 2022). "This study attempted to explore the value of preoperative NMP22 and CSTB expression in evaluating the recurrence of bladder cancer after surgery." (PMID 35647202, 2022). "The results of ROC curve analysis showed that the AUC of preoperative NMP22 and CSTB expression levels to assess postoperative recurrence of bladder cancer was 0.696 and 0.659, respectively (P < 0.05)." (PMID 35647202, 2022). "CSTB has also been reported to serve as a prognostic biomarker for bladder cancer, lung cancer and colorectal cancer." (PMID 35078458, 2022). "The results manifested that NMP22 and CSTB were isolated influencing factors of postoperative recurrence of bladder carcinoma (OR = 1.042, 2.307, P < 0.05)." (PMID 35647202, 2022). "CSTB is a tissue and urinary biomarker for bladder cancer recurrence and disease progression." (PMID 26911362, 2016). "However, in bladder cancer, urine levels of CSTB are positively correlated with tumor grade, stage and shorter time to disease recurrence and progression." (PMID 24452274, 2014). "In bladder cancer tissues, CST1, CST2, CST6, CSTA, and CSTB were significantly upregulated, while CST3 and CST7 were downregulated compared to benign tissues." (PMID 40747123, 2025). "CST6, CSTA, and CSTB were upregulated, while CST3 and CST7 were downregulated in bladder cancer tissues." (PMID 40747123, 2025). "ROC curve analysis showed that the AUC of postoperative recurrence of bladder carcinoma assessed by preoperative NMP22 and CSTB levels was 0.696 (95% CI: 0.591-0.800) and 0.659 (95% CI: 0.553-0.765), respectively." (PMID 35647202, 2022). "The results suggest that the combined testing of NMP22 and CSTB is more valuable than NMP22 and CSTB alone in assessing the postoperative recurrence of bladder carcinoma." (PMID 35647202, 2022). "The sensitivity, specificity, accuracy, positive predictive value, and negative predictive value of NMP22 and CSTB single detection and combined detection were evaluated for postoperative recurrence of bladder cancer." (PMID 35647202, 2022).